ATF4 (activating transcription factor 4)
Description:
Transcription factor that binds the cAMP response element (CRE) (consensus: 5'-GTGACGT[AC][AG]-3') and displays two biological functions, as regulator of metabolic and redox processes under normal cellular conditions, and as master transcription factor during integrated stress response (ISR). Binds to asymmetric CRE's as a heterodimer and to palindromic CRE's as a homodimer (By similarity). Core effector of the ISR, which is required for adaptation to various stress such as endoplasmic reticulum (ER) stress, amino acid starvation, mitochondrial stress or oxidative stress. During ISR, ATF4 translation is induced via an alternative ribosome translation re-initiation mechanism in response to EIF2S1/eIF-2-alpha phosphorylation, and stress-induced ATF4 acts as a master transcription factor of stress-responsive genes in order to promote cell recovery. Promotes the transcription of genes linked to amino acid sufficiency and resistance to oxidative stress to protect cells against metabolic consequences of ER oxidation (By similarity). Activates the transcription of NLRP1, possibly in concert with other factors in response to ER stress. Activates the transcription of asparagine synthetase (ASNS) in response to amino acid deprivation or ER stress. However, when associated with DDIT3/CHOP, the transcriptional activation of the ASNS gene is inhibited in response to amino acid deprivation. Together with DDIT3/CHOP, mediates programmed cell death by promoting the expression of genes involved in cellular amino acid metabolic processes, mRNA translation and the terminal unfolded protein response (terminal UPR), a cellular response that elicits programmed cell death when ER stress is prolonged and unresolved (By similarity). Activates the expression of COX7A2L/SCAF1 downstream of the EIF2AK3/PERK-mediated unfolded protein response, thereby promoting formation of respiratory chain supercomplexes and increasing mitochondrial oxidative phosphorylation. Together with DDIT3/CHOP, activates the transcription of the IRS-regulator TRIB3 and promotes ER stress-induced neuronal cell death by regulating the expression of BBC3/PUMA in response to ER stress. May cooperate with the UPR transcriptional regulator QRICH1 to regulate ER protein homeostasis which is critical for cell viability in response to ER stress. In the absence of stress, ATF4 translation is at low levels and it is required for normal metabolic processes such as embryonic lens formation, fetal liver hematopoiesis, bone development and synaptic plasticity (By similarity). Acts as a regulator of osteoblast differentiation in response to phosphorylation by RPS6KA3/RSK2: phosphorylation in osteoblasts enhances transactivation activity and promotes expression of osteoblast-specific genes and post-transcriptionally regulates the synthesis of Type I collagen, the main constituent of the bone matrix. Cooperates with FOXO1 in osteoblasts to regulate glucose homeostasis through suppression of beta-cell production and decrease in insulin production (By similarity). Activates transcription of SIRT4 (By similarity). Regulates the circadian expression of the core clock component PER2 and the serotonin transporter SLC6A4 (By similarity). Binds in a circadian time-dependent manner to the cAMP response elements (CRE) in the SLC6A4 and PER2 promoters and periodically activates the transcription of these genes (By similarity). Mainly acts as a transcriptional activator in cellular stress adaptation, but it can also act as a transcriptional repressor: acts as a regulator of synaptic plasticity by repressing transcription, thereby inhibiting induction and maintenance of long-term memory (By similarity). Regulates synaptic functions via interaction with DISC1 in neurons, which inhibits ATF4 transcription factor activity by disrupting ATF4 dimerization and DNA-binding. (Microbial infection) Binds to a Tax-responsive enhancer element in the long terminal repeat of HTLV-I.
Synonyms: CREB-2; TaxREB67; CREB2; TXREB
Tractability: Antibody: UniProt places it where antibodies can reach, with medium confidence; its Gene Ontology location is reachable by antibodies, with medium confidence. PROTAC: UniProt records ubiquitination sites on it; ubiquitination databases record sites on it.
Target class: Transcription factor
Gene: Protein-coding gene on chromosome 22 (39,519,695 to 39,522,690, forward strand). Ensembl gene ENSG00000128272.
Subcellular location: Nucleus; Nucleus speckle; Cytoplasm; Cell membrane; Cytoplasm, cytoskeleton, microtubule organizing center, centrosome
Subcellular location (Human Protein Atlas): Nucleoplasm
Pathways (Reactome):
Cellular responses to stimuli: ATF4 activates genes in response to endoplasmic reticulum stress; ATF6 (ATF6-alpha) activates chaperone genes; NFE2L2 regulating ER-stress associated genes; NFE2L2 regulating anti-oxidant/detoxification enzymes; PERK regulates gene expression; Response of EIF2AK1 (HRI) to heme deficiency; Response of EIF2AK4 (GCN2) to amino acid deficiency
Gene Ontology:
Molecular function: DNA binding; DNA-binding transcription factor activity; DNA-binding transcription factor activity, RNA polymerase II-specific; identical protein binding; leucine zipper domain binding; promoter-specific chromatin binding; protein binding; protein kinase binding; RNA polymerase II-specific DNA-binding transcription factor binding; sequence-specific DNA binding; sequence-specific double-stranded DNA binding; transcription cis-regulatory region binding; cAMP response element binding protein binding; DNA-binding transcription activator activity, RNA polymerase II-specific; protein heterodimerization activity; RNA polymerase II cis-regulatory region sequence-specific DNA binding; RNA polymerase II transcription regulatory region sequence-specific DNA binding; cAMP response element binding; DNA-binding transcription factor binding; general transcription initiation factor binding
Biological process: cellular response to amino acid starvation; cellular response to glucose starvation; cellular response to leucine starvation; cellular response to oxidative stress; HRI-mediated signaling; integrated stress response signaling; negative regulation of oxidative stress-induced neuron intrinsic apoptotic signaling pathway; PERK-mediated unfolded protein response; positive regulation of DNA-templated transcription; positive regulation of gene expression; positive regulation of transcription by RNA polymerase I; positive regulation of transcription by RNA polymerase II; positive regulation of vascular endothelial growth factor production; regulation of osteoblast differentiation; response to endoplasmic reticulum stress; response to nutrient levels; bone mineralization; cellular response to UV; circadian regulation of gene expression; embryonic hemopoiesis; endoplasmic reticulum unfolded protein response; gluconeogenesis; intrinsic apoptotic signaling pathway in response to endoplasmic reticulum stress; lens fiber cell morphogenesis; mRNA transcription by RNA polymerase II; and 17 more
Cellular component: ATF1-ATF4 transcription factor complex; ATF4-CREB1 transcription factor complex; centrosome; CHOP-ATF4 complex; cytoplasm; Lewy body core; neuron projection; nuclear periphery; nuclear speck; nucleoplasm; nucleus; protein-containing complex; RNA polymerase II transcription regulator complex; chromatin; cytosol; plasma membrane; dendrite membrane; transcription regulator complex
Genetic constraint (gnomAD): Loss-of-function variants: 8 observed, 20.11 expected, observed/expected ratio (o/e) 0.4, 90% interval 0.23 to 0.72. The synonymous counts are far from expectation, so gnomAD's model fits this gene poorly and the ratio says little. Missense variants: 544 observed, 422.39 expected, observed/expected ratio (o/e) 1.29, 90% interval 1.2 to 1.38. Synonymous variants: 240 observed, 167.09 expected, observed/expected ratio (o/e) 1.44, 90% interval 1.29 to 1.6.
Homologues: Orthologues: chimpanzee ATF4 (99% identical), macaque ATF4 (98% identical), dog ATF4 (91% identical), guinea pig ATF4 (88% identical), rat Atf4 (87% identical), mouse Atf4 (87% identical), pig ATF4 (86% identical), tropical clawed frog atf4 (56% identical), zebrafish atf4a (35% identical), zebrafish atf4b (33% identical), Caenorhabditis elegans atfs-1 (22% identical), Caenorhabditis elegans atf-4 (13% identical). Paralogues in human: ATF5 (23% identical).
Diseases named in the same sentence as ATF4 in open-access papers:
ATF4 is named in the same sentence as 347 diseases in open-access papers, as found by Europe PMC text mining. Sharing a sentence is not in itself a finding about the gene and the disease. The quoted sentences say what the papers report.
breast cancer (117 papers, 2010 to 2026). A primary or metastatic malignant neoplasm involving the breast. "ATF4 is a transcription factor that is associated with the progression of different cancers, such as breast cancer, lung cancer, and melanoma." (PMID 36733341, 2023). "MDA-MB-231 breast cancer cells were treated with CB-839 for 8 h; cross-linked chromatin was then digested to a length of ~150–900 bp, and an antibody against ATF4 was used to precipitate ATF4/DNA complexes." (PMID 35963851, 2022). "The association between ATF4 levels and survival in patients with breast cancer was assessed using KMplotter." (PMID 35847893, 2022). "Moreover, ATF4 is associated with the initiation and progression of glioblastoma, hepatocellular carcinoma, colorectal cancer, gastric cancer, breast cancer, prostate cancer and lung cancer." (PMID 38601083, 2024). "Moreover, the eIF2α/ATF4 axis is associated with radioresistance through the modulation of glutathione biosynthesis and ROS generation in breast cancer." (PMID 39261452, 2024). "High levels of ATF4 in patients with breast cancer were associated with poorer overall survival and relapse-free survival when patient data were split by upper quartile of expression compared to the lower three quartiles, as well as when patient data were split by median expression (data not shown)." (PMID 35847893, 2022). "Additionally, hypoxia induces ER stress and unfolded protein response and was recently linked to migration and sphere formation in breast cancer cells by activation of the PERK/ATF4/LAMP3 arm under hypoxic conditions." (PMID 25849745, 2015). "Next, we confirmed through nuclear–cytoplasmic fractionation that tramadol-induced ATF4 translocated to the nucleus in both breast cancer cell lines." (PMID 41526224, 2026). "From a translational standpoint, the identification of tramadol as a modulator of the HIF-1α/ATF4 axis provides new insights into therapeutic strategies targeting stress-adaptive pathways in resistant breast cancer subtypes." (PMID 41526224, 2026). "Inhibit KDM4B, upregulating UPR target ATF4 and triggering apoptosis in PTEN-deficient breast cancer cells." (PMID 41301006, 2025). "Used in breast cancer, but combined with KDM4B inhibitors to sensitize PTEN-deficient tumors to apoptosis by inducing UPR and activating ATF4." (PMID 41301006, 2025). "In breast cancer and lung cancer cells, ATF4 binds to cis-regulatory elements within the promoter region of the glucose transporter 1 (GLUT1) gene, significantly activating its transcription." (PMID 40830338, 2025). "Combining inhibitors of the histone demethylase KDM4B, such as methylstat and PI3K/AKT inhibitors, upregulates the UPR downstream target ATF4, resulting in UPR activation and the apoptosis of PTEN-deficient breast cancer cells." (PMID 41301006, 2025). "In another study, ATF4 upregulated the expression of LAMP3 to promote cell migration in breast cancer cells under hypoxic conditions." (PMID 39090107, 2024). "The change in GPT2 in murine mammary cancer cells expression was accompanied by the increase of the ATF4." (PMID 38808274, 2024). "Depletion of ATF4 also decreases metastasis and tumor growth in breast cancer by mediating the TGF-β/SMAD and mTOR/RAC1-RHOA pathways." (PMID 39261452, 2024). "The knockout of ATF4 or CHOP delayed paraptosis induced by the diterpenoid vinigrol in MCF-7 breast cancer cells." (PMID 39497143, 2024). "For the upstream regulation of PSAT1, we previously reported that PSAT1 can be transcriptionally activated by the transcription factor ATF4 in breast cancer." (PMID 39199378, 2024). "VCP inhibition by pharmacological compounds or siRNAs induces paraptosis in breast cancer cells by restoring the translation of ATF4 and DDIT4 via eukaryotic translation initiation factor 3 subunit D (eIF3d)." (PMID 39497143, 2024). "When breast cancer cells are exposed to bortezomib, ATF4 is induced and triggers autophagy, which promotes breast cancer cell survival." (PMID 38297380, 2024).
breast cancer (continued). "Further, proteasome inhibition induces LAMP3 expression in an ATF4-dependent manner in breast cancer cells." (PMID 37062845, 2023). "We observed an increased level of ATF4 under matrix-deprived conditions in both breast cancer cell lines." (PMID 37425300, 2023). "Nodakenin induced apoptosis and upregulated ER stress-related proteins (the phosphorylation of PERK and eIF2α and the expression of GRP78, CHOP, and ATF4) via the upregulation of Nox4 and ROS and Ca2+ release in breast cancer cells." (PMID 36830050, 2023). "ATF4 is a classical downstream target of eIF2α phosphorylation and plays a vital role in breast cancer cell migration and invasion." (PMID 37834012, 2023). "We also demonstrate an upregulation of ATF4 in matrix-deprived breast cancer cells, thus indicating both the activation of ISR pathway as well as existence of altered translation." (PMID 37425300, 2023). "Another possible treatment of breast cancer is bortezomib, that leads to an ATF4-dependent increase in LC3B and autophagy, favouring bortezomib-resistance." (PMID 36675080, 2023). "Only during knockdown of PERK, ATF4 or LAMP3 can enhance the sensitivity of breast cancer cells to radiotherapy." (PMID 36675080, 2023). "In ER+ breast cancer, phosphorylation of EIF2α by salubrinal induced ATF4 and C/EBP, triggering apoptosis, which was potentiated by 4-hydroxytamoxifen." (PMID 38001610, 2023). "This was shown by our findings that activating transcription factor 4 (ATF4) amplification and a higher ATF4-driven gene expression program in a subset of breast cancer cells provides a survival advantage under hypoxia and lactic acidosis." (PMID 37568677, 2023). "For example, breast cancer, colorectal cancer, prostate cancer, and ATF4 are all involved in tumorigenesis." (PMID 36900220, 2023). "High ATF4 expression correlated with tumor relapse, metastasis, and reduced overall survival of patients with breast cancer, adenoid cystic carcinoma (ACC), osteosarcoma, glioma, and kidney renal clear cell carcinoma (KIRC)." (PMID 36739602, 2023). "This led us to Sirt5, as we found a positive correlation between ATF4 and Sirt5 expression when analyzing data from The Cancer Genome Atlas (TCGA) breast cancer data set (3380 samples)." (PMID 35963851, 2022). "As the expression of ATF4 provides a protective benefit in breast cancer cells challenged with metabolic stress, we next wanted to identify transcriptional targets of ATF4 that play a functional role in this stress response." (PMID 35963851, 2022). "Here, we describe a unique signaling pathway that triggers the upregulation of ATF4 expression in breast cancers challenged with metabolic stress." (PMID 35963851, 2022). "Crosstalk between NFκB and ATF4 has yet to be studied in ER + breast cancer, and likewise, the mechanistic relationship between NFκB and ISR remains to be clarified." (PMID 35264224, 2022). "The same was true when knocking down ATF4 in BT549 breast cancer cells treated with CB-839 or deprived of glutamine." (PMID 35963851, 2022). "Together, these data demonstrate the presence of a metabolic stress-sensing pathway that helps to extend the lifetime of ATF4 in order to ensure the survival of breast cancer cells." (PMID 35963851, 2022). "In contrast, the Nrf2 activator, AI-1, markedly increased the protein and transcript levels of ATF4 in breast cancer cells either treated with CB-839 or deprived of glutamine." (PMID 35963851, 2022). "We show that mTORC2 enhances ATF4 expression and identify Sirt5 as an ATF4 transcriptional target which is necessary to promote breast cancer survival in response to metabolic stress." (PMID 35963851, 2022). "In a study of breast cancer, it was suggested that Creb3l1 was a target of downstream effector ATF4." (PMID 35803572, 2022). "We next set out to establish that Sirt5 is a transcriptional target of ATF4 by examining the effects of knocking down its expression in breast cancer cells undergoing metabolic stress." (PMID 35963851, 2022).